UGGT1 (UDP-glucose glycoprotein glucosyltransferase 1)
Description:
Recognizes glycoproteins with minor folding defects. Reglucosylates single N-glycans near the misfolded part of the protein, thus providing quality control for protein folding in the endoplasmic reticulum. Reglucosylated proteins are recognized by calreticulin for recycling to the endoplasmic reticulum and refolding or degradation.
Synonyms: UGT1; hUGT1; UGCGL1; CDG2CC
Tractability: Antibody: UniProt predicts a signal peptide or a membrane-spanning region. PROTAC: ubiquitination databases record sites on it; its protein half-life has been measured.
Target class: Enzyme; Transferase
Gene: Protein-coding gene on chromosome 2 (128,091,151 to 128,195,677, forward strand). Ensembl gene ENSG00000136731.
Subcellular location: Endoplasmic reticulum lumen; Endoplasmic reticulum- Golgi intermediate compartment
Subcellular location (Human Protein Atlas): Cytosol; Primary cilium; Primary cilium transition zone
Pathways (Reactome):
Metabolism of proteins: ER Quality Control Compartment (ERQC)
Gene Ontology:
Molecular function: protein binding; UDP-glucose:glycoprotein glucosyltransferase activity
Biological process: 'de novo' post-translational protein folding; endoplasmic reticulum mannose trimming; glycoprotein biosynthetic process; UDP-glucosylation
Cellular component: endoplasmic reticulum; endoplasmic reticulum lumen; endoplasmic reticulum-Golgi intermediate compartment; extracellular exosome; protein-containing complex; endoplasmic reticulum quality control compartment
Genetic constraint (gnomAD): Loss-of-function variants: 87 observed, 168.57 expected, observed/expected ratio (o/e) 0.52, 90% interval 0.43 to 0.62. The upper end of that interval is the gene's LOEUF score, 0.62, which puts it in group 2 of 6, group 1 being the genes least tolerant of losing a copy. Missense variants: 1,473 observed, 1,731.6 expected, observed/expected ratio (o/e) 0.85, 90% interval 0.81 to 0.89. Synonymous variants: 554 observed, 612.45 expected, observed/expected ratio (o/e) 0.9, 90% interval 0.84 to 0.97.
Homologues: Orthologues: chimpanzee UGGT1 (99% identical), macaque UGGT1 (98% identical), dog UGGT1 (95% identical), pig UGGT1 (94% identical), rat Uggt1 (91% identical), mouse Uggt1 (91% identical), guinea pig UGGT1 (90% identical), rabbit UGGT1 (90% identical), tropical clawed frog uggt1 (75% identical), zebrafish uggt1 (75% identical), Drosophila melanogaster Uggt (43% identical), Caenorhabditis elegans uggt-1 (41% identical), and 1 more. Paralogues in human: UGGT2 (53% identical).
Diseases named in the same sentence as UGGT1 in open-access papers:
UGGT1 is named in the same sentence as 22 diseases in open-access papers, as found by Europe PMC text mining. Sharing a sentence is not in itself a finding about the gene and the disease. The quoted sentences say what the papers report.
glioma (2 papers, 2024 to 2025). A benign or malignant brain and spinal cord tumor that arises from glial cells (astrocytes, oligodendrocytes, ependymal cells). "Similarly, another model for predicting the prognosis of lower-grade gliomas, which is based on four RNA-edited sites (PRKCSH chr19:11561032, DSEL chr18:65174489, UGGT1 chr2:128952084, and SOD2 chr6:160101723), also reported an AUC of 0.823." (PMID 39764127, 2024).
Obesity (2 papers, 2022). Accumulation of substantial excess body fat. "Two DEGs associated with obesity in humans from the magenta module that merit further study are stress-associated endoplasmic reticulum protein 1 (Serp1) and UDP-glucose glycoprotein glucosyltransferase 1 (Uggt1)." (PMID 35945490, 2022). "For the identified DEHGs for obesity, there were six previously reported genes (UGGT1, ANO6, MPEG1, PTGS1, CLU and IQGAP1) and two novel genes (LUZP6 and PLCB2) for obesity." (PMID 35568907, 2022).
congenital disorder of glycosylation (1 paper, 2025). Congenital disorder of glycosylation (CDG) is a fast growing group of inborn errors of metabolism characterized by defective activity of enzymes that participate in glycosylation (modification of proteins and other macromolecules by adding and processing of oligosaccharide side chains). "Bi-allelic UGGT1 variants cause a distinct congenital disorder of glycosylation (UGGT1-CDG) with variable severity, characterized by neurodevelopmental impairment, seizures, dysmorphic features, and multiorgan involvement." (PMID 40267907, 2025).
corneal dystrophy (1 paper, 2024). The term corneal dystrophy embraces a heterogeneous group of bilateral genetically determined non-inflammatory corneal diseases that are usually restricted to the cornea. "Recently, it has been reported that UGGT1 is involved in the ER retention of Trop-2 mutant proteins, which are encoded by a causative gene of gelatinous drop-like corneal dystrophy." (PMID 39654396, 2024).
developmental delay (1 paper, 2025). "The clinical spectrum of UGGT1-CDG reflects that of other CDGs, which commonly cause multisystemic manifestations with developmental delay and neurological abnormalities of variable clinical severity." (PMID 40267907, 2025). "The cardinal clinical features of UGGT1-CDG involve developmental delay, intellectual disability, seizures, characteristic facial features, and microcephaly in the majority (9/11 affected individuals for whom measurements were available)." (PMID 40267907, 2025).
diabetes (1 paper, 2022). "Here, we report MODY10- or neonatal diabetes-associated proinsulin variants that interfere with their interaction with UGGT1." (PMID 36028536, 2022). "Using insulin mutagenesis of neonatal diabetes variant-C43G and maturity-onset diabetes of the young 10 (MODY10) variant-R46Q, UDP-glucose:glycoprotein glucosyltransferase 1 (UGGT1) protects cereblon-dependent proinsulin ubiquitination in the ER." (PMID 36028536, 2022). "In support of this hypothesis, C43G and C109R variants of proinsulin associated with neonatal diabetes failed to bind UGGT1." (PMID 36028536, 2022).
glioblastoma (1 paper, 2017). The most malignant astrocytic tumor (WHO grade IV). "We repeated this experiment in SF268 glioblastoma (SF268) cells to determine whether the effects of UGGT1 on viral replication are specific to a given cell type." (PMID 28545059, 2017).
low grade glioma (1 paper, 2025). A grade I or grade II glioma arising from the central nervous system. "Recent studies have implicated UGGT1 in cancer, particularly in low-grade gliomas (LGG), where increased UGGT1 expression correlates with poor prognosis." (PMID 40507918, 2025).
neurodevelopmental disabilities (1 paper, 2025).
neutropenia (1 paper, 2025). A decrease in the number of neutrophils found in the blood. "Although episodic neutropenia was reported in family 8, it is unclear whether this represents a rare feature of UGGT1-CDG or an unrecognized dual molecular diagnosis due to multilocus pathogenic variation within the family." (PMID 40267907, 2025).
psoriasis (1 paper, 2024). An autoimmune condition characterized by red, well-delineated plaques with silvery scales that are usually on the extensor surfaces and scalp. "Taking the intersection of these two algorithms, we finally obtained four specific gene biomarkers for psoriasis diagnosis (UGGT1\MMP9\CCNE1\ARHGEF28)." (PMID 38803495, 2024). "RT-qPCR results showed that compared to normal human epidermis, the expression of UGGT1, CCNE1, and MMP9 was significantly increased in patients with psoriasis, while ARHGEF28 expression was significantly decreased." (PMID 38803495, 2024).
virus infection (1 paper, 2017). "In S5 Fig, we found that UGGT1 associated with JEV polymerase NS5 upon viral infection, and enhanced viral pathogenicity." (PMID 28545059, 2017). "Together, these findings confirm that upon viral infection, UGGT1 levels increase, and UGGT1 co-precipitates with 3D polymerase and other factors on membranous replication complexes." (PMID 28545059, 2017). "In this study, we showed that expression of the key UPR factor, UGGT1, not only increases upon viral infection, but UGGT1 interaction with the EVA71 3D polymerase also has positive effects on viral growth and pathogenicity as well." (PMID 28545059, 2017). "Host cells can mobilize the UPR in an attempt to restrict viral infection, and UGGT1 is known to be a key UPR factor in the ER." (PMID 28545059, 2017). "The proportion of UGGT1 external to the ER rose from 11% to 37% upon viral infection (lane 3 and 4)." (PMID 28545059, 2017). "UGGT1 expression levels were found to increase upon viral infection (input lysate)." (PMID 28545059, 2017). "This is the first study to describe the deployment of an ER protein to the cytosol upon viral infection, and the interesting role of UGGT1 in EVA71 replication suggests that it may provide insight into the development of novel anti-EVA71 strategies." (PMID 28545059, 2017). "To further ascertain if UGGT1 plays a similarly important role in other virus families with regard to enhancing virulence and pathogenicity, we selected the Japanese Encephalitis Virus (JEV) from the family Flaviviridae to study the role of UGGT1 upon virus infection." (PMID 28545059, 2017).
infection (4 papers, 2017 to 2025). The state of being infected such as from the introduction of a foreign agent such as serum, vaccine, antigenic substance or organism. "UDP-Glucose: Glycoprotein Glucosyltransferase 1 (UGGT1) is expelled from the ER under conditions of ER stress, a phenomenon that has functional implications during enterovirus A71 (EV-A71) infection." (PMID 40839310, 2025). "To determine the localization of UGGT1 in cells following EVA71 infection, we used an anti-calnexin (CNX) antibody to evaluate proteins located in the ER in an immunoprecipitation assay." (PMID 28545059, 2017). "To avoid siRNA off-target effects, we used EVA71 to infect cells overexpressing UGGT1, and subsequently measured virus yields at 4, 6, and 8 h post-infection." (PMID 28545059, 2017). "Immunoprecipitation assays and MALDI-TOF analysis results indicate that the 3D viral polymerase co-precipitates with UGGT1 during EVA71 infection, and this interaction promotes EVA71 replication." (PMID 28545059, 2017). "We also noted that UGGT1 deploys from the ER to the cytosol upon EVA71 infection, where it enhances 3D polymerase levels in the membrane fraction involved in RC formation; this process is facilitated by viral protein 3A, which acts to enhance the amount of UGGT1 in the membrane fraction." (PMID 28545059, 2017). "Infected wild-type mice began to die on Day 8 after infection, whereas heterozygous Uggt1 knockout mice began to die on Day 10; however, the 90% survival rate in infected heterozygous knockout mice was still significantly higher (P < 0.001) than the 0% survival in wild-type mice." (PMID 28545059, 2017). "Importantly, during EVA71 infection, we found that UGGT1 expression levels increase, and UGGT1 also redeploys from the ER to the cytoplasm, where it acts as a positive regulator of viral RNA synthesis." (PMID 28545059, 2017). "Importantly, HCV entry and infection were impaired in the presence of UGGT1 siRNA." (PMID 31551978, 2019). "UGGT1 was predominantly located within the ER microsome in the mock cell lysates (lanes 3 and 5); however, during EVA71 infection, UGGT1 was found to deploy out of the ER microsome." (PMID 28545059, 2017). "A mutant of UGGT1 lacking monoglucosylation activity was as efficient in promoting EV-A71 infection as wild type UGGT1, suggesting a non-canonical role in promoting viral replication." (PMID 33499355, 2021). "In mock-infected cells, UGGT1 was predominantly localized in the cytoplasm, while in EVA71-infected cells, both the 3D polymerase and UGGT1 were localized in the cytoplasm at 6 h post-infection." (PMID 28545059, 2017). "Moreover, HCV entry and infection were reduced by the absence of UGGT1." (PMID 31551978, 2019). "In the absence of infection, UGGT1 and CNX were shown to colocalize in the ER, but some UGGT1 began deploying out of the ER to colocalize with the 3D viral polymerase upon EVA71 infection, to the point where little UGGT1 remained in the ER with CNX." (PMID 28545059, 2017). "To ascertain the effect of UGGT1 on viral replication and propagation, we infected (negative control) NC or UGGT1 siRNA-transfected cells with a high titer of EVA71 (MOI = 10), and assessed 3D polymerase expression at 6 h post-infection by confocal microscopy." (PMID 28545059, 2017).
tumour (1 paper, 2025). "The expression levels of ATXN3, METTL2A, PEX26 and UGGT1 in tumour cells were higher than those in normal mammary epithelial cells, and their expression in BRCA tissues was higher than that in normal adjacent tissues." (PMID 40995818, 2025). "The expression levels of ATXN3 | chr14:92526779, LOC100130744 | chr5:14716392, METTL2A | chr17:60528133, PEX26 | chr22:18572607 and UGGT1 | chr2:128949284 in tumour tissues were significantly higher than those in normal tissues (p < 0.05)." (PMID 40995818, 2025).
UGGT1 also shares sentences with these, for which no sentence is quoted: Hyperbilirubinemia (3 papers); cancer (2); colonic carcinoma (1); Intellectual disability (1); maturity-onset diabetes of the young (1); microcephaly (1); protein folding diseases (1); schizophrenia (1).